INS (insulin)
Diseases named in the same sentence as INS in open-access papers (continued):
Sharing a sentence is not in itself a finding about the gene and the disease.
Insulin resistance (continued). "Therefore, understanding the role that integrin and its associated structural proteins plays in insulin action and glucose transport in skeletal muscle may be fundamental to identify new therapeutic targets for the treatment of insulin resistance and T2D." (PMID 36054466, 2022). "In vitro data indicate that ceramide inhibits insulin signaling, primarily through inactivation of protein kinase B, and in vivo data suggest that ceramide accumulation in muscle cells may be associated with the development of insulin resistance." (PMID 35885586, 2022). "The expression profiles in T2D donors were partially like those in children, demonstrating the dedifferentiation process that causes the dysfunction of insulin secretion, which may be one of the key mechanisms in the development of T2D, along with insulin resistance." (PMID 35885959, 2022). "Furthermore, a large genetic analysis of seven discovery cohorts together with four replication cohorts of European ancestry revealed evidence of IL-1Ra raising by its SNP variation associated with lower fasting insulin and an improved homeostasis model assessment of insulin resistance." (PMID 36014927, 2022). "Furthermore, it was found that intentional weight gain in lean participants until body mass index increased by 2 points caused insulin resistance and decreased plasma insulin clearance during basal conditions and after glucose ingestion, whereas insulin secretion was unchanged." (PMID 35054781, 2022). "In addition to hyperglycemia, loss of insulin signaling due to insulin resistance or insulinopenia may also contribute to the development of DPN." (PMID 36615728, 2022). "Reduced insulin clearance has increasingly been recognized as an integral part of insulin resistance, irrespective of whether it plays a causal or an adaptive role in insulin resistance." (PMID 36009446, 2022). "However, studies in non-pregnant people have found that total dietary protein intake was positively associated with insulin resistance levels, which indicated that the regulation of insulin might be impacted by dietary protein." (PMID 36501068, 2022). "Considering these findings, although our analysis was conducted in a different area of the body, we speculate that an alteration of miR-127-3p could interfere with the insulin pathway, for instance in SC adipose tissue, ultimately causing insulin resistance, a typical mark of the HALS." (PMID 35408847, 2022). "Insulin resistance is associated with the occurrence of vascular-related conditions including hypertension, atherosclerosis, and endothelial dysfunction, and insulin plays an important role in conduit arteries compliance, modulation of blood flow and relaxation of resistance arterioles." (PMID 36237532, 2022). "Interestingly, IN administration of 40 IU long-acting insulin analog (detemir) improved peripheral insulin resistance during treatment, which was associated with improved verbal memory in AD patients that carry APOE ε4, unlike what had been previously reported with rapid acting insulin analogs." (PMID 36429060, 2022). "Therefore, SPARC deficiency would reduce insulin secretion (independently of insulin resistance)." (PMID 35208200, 2022). "Furthermore, the transduction of insulin signals may be interfered with by inflammatory factors, resulting in insulin resistance, which then causes various metabolic disorders." (PMID 35407029, 2022). "Thus, contrary to the prevailing opinion that cortisol causes insulin resistance (in all tissues of the body), increased visceral adiposity may be in fact due to synergistic effects of insulin and cortisol on fat cells." (PMID 35897752, 2022). "On the other hand, in a PD rodent model, a depletion of dopaminergic neurons was also found to alter insulin signaling and was associated with increased markers of insulin resistance, which could lead to a vicious cycle with progressive insulin resistance and a loss of dopaminergic neurons." (PMID 35956417, 2022).
Insulin resistance (continued). "Insulin resistance (IR) is a pathological condition caused by genetic and environmental factors, in which insulin promotes the decrease of glucose uptake and utilization rate, as well as the body’s decreased responsiveness and sensitivity to the physiological action of insulin." (PMID 35937809, 2022). "Moreover, studies have indicated that poor sleep efficiency may cause reduced insulin sensitivity, impaired glucose tolerance, and decreased acute insulin resistance." (PMID 35546663, 2022). "In HFrEF patients, insulin resistance might be linked to impaired tissue perfusion secondary to hemodynamic failure and to impaired blood glucose transport, while in HFpEF, insulin resistance might be caused by an insufficient insulin cellular signaling." (PMID 36547453, 2022). "In this review, we use insulin and AD as an entry point, summarize the underlying mechanisms by which insulin affects memory, and discuss the potential molecular link between insulin resistance and AD, which may help the future development of novel targets and new treatment options." (PMID 36430894, 2022). "In addition to insulin, a recent finding suggested the role of the resistin hormone in an association between obesity and type 2 diabetes, and it represents a potential candidate for the etiology of insulin resistance." (PMID 36135388, 2022). "Because elevated flux through the HBP has been associated with insulin resistance and diabetic complications in rats, we tested the effect of chronic GlcNAc supplementation on glucose utilization by measuring blood glucose clearance and insulin‐stimulated glucose utilization." (PMID 36124412, 2022). "Indeed, in the sporadic UCD-T2DM rat model, the development of peripheral insulin resistance was associated with the hippocampal desensitization of the insulin pathway, resulting in enhanced lipid peroxidation (4-HNE) levels that were inversely correlated with those of PGC-1α." (PMID 36117625, 2022). "However, E2 decreases insulin resistance and T, whereby low levels are associated with diminished insulin sensitivity, and may elicit an increase in insulin resistance in the WAT of female rats." (PMID 36233256, 2022). "Furthermore, it was found to be a strong human endocrine disruptor that affects serum testosterone and is subsequently linked to higher glucose and insulin levels, obesity, the distribution of fat in the upper body, and is strongly linked to insulin resistance and the other metabolic syndrome." (PMID 36552644, 2022). "The exact underlying mechanism through which disrupted insulin signaling manifests is yet to be clear; however, emerging evidence is shedding light on inflammatory factors and oxidative stress, suggesting they mediate insulin resistance, leading to GDM manifestation." (PMID 35408874, 2022). "Noteworthy, significant correlations between ferritin and glucose (r = 0.39, p = 0.0041), HbA1c (r = 0.46, p = 0.0027), and insulin levels (r = 0.34, p = 0.018) were found, denoting an association between iron and glucose homeostasis in obesity-associated insulin resistance." (PMID 36551793, 2022). "Insulin resistance is defined as a loss of response of target tissues to insulin stimulation, which critically affects the control of glycemia, leading to hyperglycemia and contributing to type 2 diabetes (T2D), as well as lipid metabolism, notably through the loss of insulin anti-lipolytic action." (PMID 36140242, 2022). "Type 2 diabetes is initiated by peripheral insulin resistance but eventually progresses to the dysfunction and loss of β-cells, which are a critical group of pancreatic cells that regulate glucose homeostasis by producing and secreting insulin in response to blood glucose level changes." (PMID 35563231, 2022).
Insulin resistance (continued). "Increased mTOR activation in skeletal muscle of humans with obesity in the fasted state may result from effects of an obesity-associated insulin resistance on increasing the plasma amino acids, and given the role of increased concentrations of plasma amino acids (and insulin) in activating mTOR." (PMID 35350688, 2022). "In healthy subjects, insulin resistance status can change rapidly because of many factors such as physical activity, food intake, psychological condition, the presence of other metabolic stresses, and hormonal changes associated with glucose and insulin homeostasis." (PMID 35075363, 2022). "Thus, a lowered IRS-1 protein alone in the muscle of OZRs might trigger the progression of insulin resistance since this defect would diminish downstream insulin signaling to cause a reduction in glucose disposal." (PMID 36547071, 2022). "The current study quantifies plasma sphingolipid species from these various classes to determine whether there are differences early in the development of insulin resistance, prior to loss of euglycemia, and if sphingolipid changes correlate with other insulin responsive biomolecules such DAG." (PMID 35705631, 2022). "This implies that the lower irisin levels seen in PWS reflects their healthier glucose homeostasis as compared to obese controls, while the association documented between irisin and post-OGTT insulin levels could reflect its association with hyperinsulineamia and insulin resistance." (PMID 35774143, 2022). "Indeed, previous studies show that corticosterone flattening, albeit at a higher total exposure, causes elevated plasma insulin levels and insulin resistance, but it is unclear whether this contributes to the altered TG-derived FA uptake in BAT." (PMID 33548499, 2021). "There is an inverse relationship between insulin sensitivity index and baseline lactate level, and it is still controversial whether obesity-related hyperlactatemia is a consequence of insulin resistance, exclusively due to obesity itself or associated with other factors." (PMID 34133526, 2021). "Finally, metabolic and hormonal disruption due to stress may impact adipose tissues and influence insulin levels and the risk for insulin resistance." (PMID 34063694, 2021). "In T2DM, the imbalances between specific metals might have a role in upsetting normal glucose and insulin metabolism, and variations in the status of trace minerals can also elevate the oxidative stress that might cause insulin resistance and diabetic complications." (PMID 34066324, 2021). "However, based on evidence, it is likely that the pathogenesis of NMOSD might have caused higher insulin level and insulin resistance as a result." (PMID 33879088, 2021). "Chronic vitamin D deficiency can also trigger secondary hyperparathyroidism, increased insulin resistance (impaired pancreatic β cell function) with increased risk of metabolic syndrome, and type II diabetes mellitus (calcitriol regulates the genes involved in insulin production in the pancreas)." (PMID 34070202, 2021). "Previous studies showed that this local high-fat diet could induce obesity, hyperglycemia associated to glucose intolerance (possibility of insulin resistance), and dyslipidemia by modifying lipid and glucide metabolism probably by altering the action of insulin." (PMID 34457019, 2021). "In addition, HCV infection can induce changes in insulin signaling, causing a blockage in the release and action of insulin and thereby preventing its role in regulating glucose metabolism in the body, that is, it directly promotes insulin resistance." (PMID 34852140, 2021). "In BSB, 8 weeks of feeding with a high-carbohydrate diet upregulated the genes associated with insulin signaling pathways, which may lead to the development of insulin resistance in hepatocytes, pathological liver changes, and, eventually, nonalcoholic fatty liver disease." (PMID 34011285, 2021).
Insulin resistance (continued). "Given the facts that sunitinib has multiple pharmacological targets and that sunitinib treatment affects insulin clearance and insulin sensitivity, we therefore hypothesized that sunitinib-induced hypertension is associated with insulin resistance, insulin signaling and Pellino-1/AKT/eNOS pathways." (PMID 33841146, 2021). "However, systemic OSTN treatment might cause insulin resistance via inhibiting insulin-stimulated glycogen synthesis and glucose uptake in skeletal myocytes." (PMID 34135313, 2021). "Therefore, the increase in insulin clearance observed in our study may be interpreted as a positive effect of the diet associated with the reduced body weight and whole-body/hepatic insulin resistance." (PMID 33919503, 2021). "Therefore, we can recognize that Sestrin2 is a potential insulin sensitizer, and that Sestrin deficiency and/or dysfunction may lead to insulin resistance, which can lead to the development of diabetes." (PMID 34803916, 2021). "Since galanin elevates insulin sensitivity via causing an increase in GLUT-4 translocation and a decrease in insulin secretion from the pancreas, the results of the present study made us hypothesise that galanin deficiency is associated with insulin resistance in the group of PCOS patients." (PMID 33740336, 2021). "This is supported with our OGTT findings in HFD group whereby significant increases of glucose concentrations were observed following glucose loading, indicating an impaired insulin function, which could be linked to insulin resistance after prolonged HFD feeding." (PMID 34822647, 2021). "Moreover, maternal 1- and 2-h PG levels were also associated with child insulin resistance and impaired insulin secretion, suggesting that children exposed in utero to higher glucose levels may be at higher risk for progression to T2DM." (PMID 34108933, 2021). "Taken together, these findings suggest that AD pathological processes may be triggered or exacerbated by peripheral insulin resistance and that Aβ may itself induce brain insulin resistance and synapse loss, raising the possibility that insulin treatment may correct these pathological events." (PMID 34573112, 2021). "Additionally, systemic inflammation plays an important role in the pathogenesis of prediabetes and T2DM, given that the adipose tissue can overproduce pro-inflammatory cytokines like TNF-α, which impairs insulin signalling, increasing the risk of insulin resistance." (PMID 33578998, 2021). "The observation that insulin and insulin-like growth factor (IGF) 1 signaling also triggers distinct changes in lncRNA expression (e.g., the lncRNA CRNDE) points to the fact that lncRNAs may also be implicated in the metabolic effects of insulin and the development of insulin resistance." (PMID 34572306, 2021). "Furthermore, insulin resistance has been linked to hypothyroidism in a number of preclinical and in vitro investigations, where it was discovered that peripheral muscles become less sensitive to insulin under hypothyroid conditions." (PMID 35106234, 2021). "Besides, insulin resistance has also been linked to hypertension as insulin is able to cross the blood–brain barrier and subsequently activate the systemic nervous system, in addition to its ability to upregulate the angiotensin II (AT-II) receptor and reduce NO." (PMID 34576959, 2021). "In addition, changes in insulin signaling, caused inter alia insulin resistance, may accelerate brain aging, and affect plasticity and possibly neurodegeneration." (PMID 34576151, 2021). "Additionally, caffeine significantly improved the hyperglycemia, high serum insulin, and insulin resistance index caused by the HFHC diet, whereas EGCG only reduced serum insulin and the insulin resistance index but was unable to reverse HFHC-induced hyperglycemia." (PMID 34881283, 2021).
Insulin resistance (continued). "Thus, the observed increase in pantothenic acid may be associated with changes in insulin sensitivity and insulin resistance, thereby increasing the risk of GDM; however, the underlying mechanism needs to be further studied." (PMID 33628838, 2021). "The higher expression of Na+/K+ α1 and α2 subunits observed in the men with type 2 diabetes may be explained by the high plasma insulin levels associated with the progressing insulin resistance in these individuals, as insulin has been observed to increase the expression of Na+/K+ pump subunits." (PMID 33426802, 2021). "Furthermore, peripheral insulin resistance is associated with impaired brain insulin action." (PMID 34070553, 2021). "Both insulin resistance and an increased risk of type 2 diabetes have also been associated with smoking tobacco, which may be due to the reported association between nicotine and reduced insulin sensitivity." (PMID 34442147, 2021). "Over time, the chronic and acute insulin resistance and inflammation independently associated with obesity and pregnancy, respectively, may lead to a progressive loss of insulin secretion that increases the risk of developing diabetes and other diseases later in life." (PMID 33827659, 2021). "Hence, we do not know whether the higher percentage of monocytes we observe in the obese/overweight insulin-resistant individuals is a cause or consequence of insulin resistance." (PMID 34886800, 2021). "Interestingly, it has been previously shown that viral infections can increase leukocyte interferon production and may cause systemic insulin resistance or muscle insulin resistance." (PMID 34886800, 2021). "This raises the distinct possibility that a β-cell defect in insulin secretion that initially causes inappropriate hypersecretion of insulin at basal plasma glucose concentrations may be a driver of insulin resistance by insulin-induced downregulation of insulin receptors." (PMID 34360563, 2021). "NAFLD, hepatic iron load, and metabolic abnormalities such as increased fasting insulin, insulin resistance, and platelet count might be linked together, and treating patients at early stages might prevent extrahepatic complications as well as the adverse clinical outcomes." (PMID 34300354, 2021). "Postmortem analysis has revealed that insulin resistance (IR) also occur in AD patients brain with significantly decreased expression of the insulin receptor, concomitant with the disease progression and indicated that the defects in insulin signaling are associated with AD pathogenesis." (PMID 34552561, 2021). "Consequently, there are disruptions in insulin signaling that may cause insulin resistance in the hippocampus and deterioration of hippocampal-dependent cognitive processes." (PMID 34444664, 2021). "Likewise, in vivo administration of selenoprotein P led to hepatic and peripheral insulin resistance, while liver-specific genetic ablation significantly ameliorated systemic glucose intolerance in association with enhanced insulin signaling in the liver and skeletal muscle." (PMID 34944728, 2021). "Because leptin synergistically acts with insulin to induce its anorexigenic actions, and considering that hypothalamic insulin resistance has been show to underlie deregulation in food intake, we wondered whether insulin signaling in the hypothalamus may be affected after a short-term HFD feeding." (PMID 34015524, 2021). "In type 2 diabetic patients treated with insulin and SGLT2i, glycemic control may be determined by an improvement of insulin resistance due to body weight loss, an improvement of glucotoxicity by insulin and/or SGLT2i, administered insulin dose, and RTG reduced because of SGLT2i." (PMID 33922546, 2021). "In addition, T2DM is caused by insulin resistance (IR) and pancreatic β-cell dysfunction, and IR is characterized by impaired insulin-mediated metabolism, which may also lead to many complications of inflammation and multiple organ damage." (PMID 32714403, 2020).